ATAD3A (ATPase family AAA domain containing 3A)
Diseases named in the same sentence as ATAD3A in open-access papers (continued):
Sharing a sentence is not in itself a finding about the gene and the disease.
tumor (continued). "Most importantly, the ATAD3A-ERK1/2 signaling axis drives HNSCC development in a RAS-independent fashion and, thus, tumor suppression is more effectively achieved when ATAD3A knockout is combined with RAS inhibitor treatment." (PMID 35093151, 2022). "Loss of ATAD3A expression suppresses HNSCC cell growth and elicits tumor regression in orthotopic tumor-bearing mice, whereas gain of ATAD3A expression produces the opposite effects." (PMID 35093151, 2022). "Other studies report that silencing ATAD3A reduces the colony formation and invasion ability of tumor cells, suggesting that ATAD3A acts as an oncoprotein." (PMID 36289190, 2022). "Bioinformatics analysis predicted ATAD3A as a direct target of miR-210-5P, the predominant miRNA induced under hypoxia in multiple solid tumors and a surrogate marker for tumor hypoxia." (PMID 33280610, 2020). "Still, the regulation of ATAD3A in the context of the tumor microenvironment remains poorly understood." (PMID 33113782, 2020). "The deregulation of ATAD3A is crucial in the tumor microenvironment because it promotes tumor metastasis." (PMID 33000861, 2020). "In MA-10 mouse tumor Leydig cells, knockdown of ATAD3A leads to a significant decrease in steroid production; and in patients with ATAD3 gene cluster deletions, derived fibroblasts display abnormalities in cholesterol metabolism." (PMID 33113782, 2020). "It is possible that the functional interaction between FAT1 and ATAD3A is one of the critical molecular mechanisms underpinning ATAD3A-induced tumor growth." (PMID 33113782, 2020). "Therefore, suppression of Atad3a reduces tumor progression by facilitating antitumor immune responses, and the effect was dependent on Pink1, indicating a crucial role of the Atad3a-Pink1 mitophagy axis in the regulation of tumor immune microenvironment." (PMID 36627348, 2023). "ATAD3A was originally identified as a tumor‐specific antigen." (PMID 38018291, 2023). "Besides, the high ATAD3A level is related to the patient's disease status and recurrence level, tumor grade, and metastasis." (PMID 38018291, 2023). "ATAD3A-low tumor in vivo might overwhelm paclitaxel effect via some suppressive mechanisms, which would be investigated in the future." (PMID 36627348, 2023). "Moreover, the expression levels of ATAD3A were higher in advanced tumor stages (II, III, and IV) than in Stage I of HNSCC, although there was no statistical significance." (PMID 35093151, 2022). "In addition to correlating with tumor stage and lymphovascular infiltration, high ATAD3A expression in LADC patients is correlated with relapse rates three-fold higher than those with low ATAD3A expression." (PMID 33113782, 2020). "Results showed that sh-ATAD3A in Huh7 cells significantly increased the tumor weight and tumor volume compared to the control group in the presence of sorafenib treatment, and miR-210-5P antagomir reduced the tumor size and tumor volume both in control and sh-ATAD3A groups." (PMID 33280610, 2020). "However, when we inoculated Atad3a-knockdown 4T1 cells into immune-competent BALB/c mice, the growth rate of tumors was reduced in comparison with control cells, suggesting that Atad3a deletion might evoke favorable immune responses to suppress tumor growth." (PMID 36627348, 2023). "Intriguingly, salirasib-induced repression in tumor growth was more significant in mice receiving ATAD3A KO HN12 cells than those implanted with the parental cells, indicating that salirasib achieves a better outcome in oral tumors with loss of ATAD3A expression." (PMID 35093151, 2022). "Targeting ATAD3A phosphorylation with the peptide TAT‐PEP shows exceptional anti‐aging and anti‐tumor effects, providing a potential therapeutic strategy for combating aging and aging‐associated disorders." (PMID 39520088, 2024).
tumor (continued). "At this stage of our understanding, ATAD3A dysfunction is required and sufficient to drive the oncogenic process of HNSCC, and depleting it has significant therapeutic effects in reducing tumor burden." (PMID 35093151, 2022). "Using these potential tumor markers to screen SMIs, we successfully identified several candidates, including AF38469 (vs. sortilin) and shikonin (vs. ATAD3A)." (PMID 29100377, 2017). "ATAD-3 and its homologs in other species (ATAD3A, ATAD3B) have been described as mitochondrial proteins with roles in tumor progression." (PMID 27506200, 2016). "Atad3a knockdown did not change the in vitro proliferation of tumor cells or their capacity to form tumors in immunodeficient BALB/c nude mice." (PMID 36627348, 2023). "In support of this hypothesis, IHC staining of paraffin tumor sections showed reduction of PD-L1+ cells, but increased infiltration of CD8+ T cells and granzyme B secretion in Atad3a-deficient tumors, with no changes in the number of Ki67+ tumor cells." (PMID 36627348, 2023). "ATAD3A overexpression was associated with a substantial decrease in cell proliferation and mammosphere formation not only in MDA-MB-468 cells but also in BT549 cells and delayed tumor growth without affecting mouse body weight." (PMID 36289190, 2022). "Additionally, we reveal that ATAD3A, a negative regulator of PINK1-dependent mitophagy, prevents PD-L1 distribution at mitochondria and degradation, thus providing new insight into mitochondria-mediated PD-L1 protein homeostasis regulation in tumor immune microenvironment." (PMID 36627348, 2023).
mitochondrial disease (10 papers, 2020 to 2026). "ATAD3A is considered one of the five most common nuclear genes associated with mitochondrial diseases in childhood." (PMID 39605788, 2024). "ATAD3A encodes for a mitochondrial ATPase whose function is unclear and has been considered one of the five most common nuclear genes associated with mitochondrial diseases in childhood." (PMID 39605788, 2024). "Recent studies have identified both recessive and dominant forms of mitochondrial disease that result from ATAD3A variants." (PMID 32004445, 2020). "ATAD3A has been previously studied in multicellular eukaryotes and has been implicated in several childhood mitochondrial diseases, with suggested functions in mitochondrial nucleoid stabilization, mitochondrial RNA translation, and mitochondrial inner membrane integrity." (PMID 42234699, 2026). "Biallelic ATAD3A deletions should be considered in cases of mitochondrial disease with spinal cord hypoplasia and PCH." (PMID 36061954, 2022). "Interestingly, mutations in TWNK, ATAD3A, and VPS35 are linked to several severe mitochondrial diseases having in common mtDNA instability, therefore representing a cluster of proteins involved in specific mtDNA turnover." (PMID 36344526, 2022).
neurological disorders (5 papers, 2019 to 2023). "In summary, our findings suggest that ATAD3A is a potential therapeutic target for combating the mitochondrial damage and neurodegeneration underlying HD and other neurological disorders that feature mitochondrial fragmentation and bioenergetic failure." (PMID 30914652, 2019). "Numerous ATAD3A mutations have been identified in patients with neurological diseases." (PMID 37569886, 2023). "Therefore, our research findings provide insights into the pathogenesis of AD and demonstrate that ATAD3A oligomerization is a potential therapeutic target for the treatment of AD and other neurological disorders associated with MAM hyperconnectivity and cholesterol disturbance." (PMID 35236834, 2022). "Among the potential physical partners, ATAD3A and 17β-HSD10, two proteins associated with neurological disorders, were confirmed using different human cell lines." (PMID 36138777, 2022).
genetic disorders (3 papers, 2020 to 2025). "Additionally, one child (ID26) carried a loss-of-function (LOF) variant in ATAD3A, associated with a known genetic disorder, but inherited from an unaffected mother." (PMID 41300846, 2025).
cardiovascular disease (1 paper, 2024). "Given the crucial relationship between mitochondrial function and cardiac health, ATAD3A-mediated mitochondrial energy supply, mitochondrial morphological homeostasis and mitochondrial antioxidant capacity could be essential mechanisms that drive cardiovascular disease susceptibility." (PMID 38250153, 2024).
head and neck tumor (1 paper, 2022). "In the present study, we show that mitochondrial ATAD3A acts as an oncogene to promote HNSCC cell growth and inhibiting it by genetic depletion or overexpression of the WA dead mutant induces head and neck tumor regression." (PMID 35093151, 2022).
infection (1 paper, 2017). The state of being infected such as from the introduction of a foreign agent such as serum, vaccine, antigenic substance or organism. "Statistical analysis results also showed that the average number of EGFP+ positive cells increased significantly after BmNPV infection with stable cell lines of ATAD3A and HSPD1 during specific periods of time." (PMID 28393927, 2017). "Western blot analyses showed that BmNPV VP39 protein increased after infection with stable cell lines of ATAD3A and HSPD1 at different time-points." (PMID 28393927, 2017). "Stable cell lines of ATAD3A and HSPD1 significantly increased BmNPV multiplication compared with pIZ-V5/His cell lines at different time points post infection." (PMID 28393927, 2017). "Furthermore, to examine whether ATAD3A and HSPD1 were involved in BmNPV infection, we analyzed the changes of BmNPV DNA replication." (PMID 28393927, 2017).
inflammation (1 paper, 2023). Aberrant reaction of the microcirculation characterized by movement of fluid and leukocytes from the blood into extravascular tissues. "The DEK/ATAD3A/DRP1 signaling axis may mediate the effects of DEK on mitophagy and NLRP3 inflammasome in asthmatic airway inflammation." (PMID 38274803, 2023).
metabolic disease (1 paper, 2023). A congenital disorder (due to inherited enzyme abnormality) or acquired (due to failure of a metabolically important organ) disorder resulting from an abnormal metabolic process. "Overall, ATAD3A’s pivotal role in the regulation of mitochondria-related activities and its implications in diverse diseases make it a promising area for future research on both mitochondrial and metabolic diseases." (PMID 37569886, 2023).
neurodegenerative disease (1 paper, 2022). A disorder of the central nervous system characterized by gradual and progressive loss of neural tissue and neurologic function. "Future investigation into the mechanism by which ATAD3A links cholesterol metabolism and mtDNA stability may provide a better understanding of the role of ATAD3A in neurodegenerative diseases." (PMID 35236834, 2022).
ATAD3A also shares sentences with these, for which no sentence is quoted: Alzheimer disease (3 papers); Cerebellar atrophy (2); optic atrophy (2); alcoholic fatty liver (1); Barth syndrome (1); cataract (1); congenital cataracts (1); congenital hydrocephalus (1); cutaneous melanoma (1); Dystonia (1); epilepsy (1); esophageal carcinoma (1); infiltrating bladder urothelial carcinoma (1); lymph node metastases (1); myocardial ischemia (1); neuroblastoma (1); neurodevelopmental disorder (1); ovarian carcinoma (1); Respiratory insufficiency (1); systemic lupus erythematosus (1); tetraplegia (1); uterine cancer (1).